MUC1 (mucin 1, cell surface associated)
Diseases named in the same sentence as MUC1 in open-access papers (continued):
Sharing a sentence is not in itself a finding about the gene and the disease.
intestinal obstruction (1 paper, 2012). Blockage of the normal flow of the intestinal contents within the bowel. "Candidate gene approaches in CF mice have revealed that decreased expression of the sodium hydrogen exchanger 3 (Nhe3) or mucin 1 (Muc1) or over-expression of the chloride calcium channel activated 3 protein (Clca3/Gob5) can reduce intestinal obstruction at weaning." (PMID 22438829, 2012).
intraductal papilloma (1 paper, 2025). An intraluminal papillary epithelial neoplasm arising within the ducts. "CK7 and MUC-1 immunohistochemical staining has certain guiding value in the diagnosis of intraductal papilloma." (PMID 40013097, 2025). "We conducted a literature review to clarify intraductal papilloma and differences between inverted ductal papilloma, highlighting the significance of CK7 and MUC-1 immunohistochemical staining in diagnosing intraductal papilloma." (PMID 40013097, 2025).
iron deficiency (1 paper, 2024). "In this study, iron deficiency and iron overload resulted in downregulation of the tight junction proteins Occludin and Claudin-1 as well as the mucosal proteins MUC1 and MUC2 in jejunum mucosa, which may contribute to a greater susceptibility of neonates to pathogen infection." (PMID 39127747, 2024).
ischemia (1 paper, 2020). A hypoperfusion of the BLOOD through an organ or tissue caused by a PATHOLOGIC CONSTRICTION or obstruction of its BLOOD VESSELS, or an absence of BLOOD CIRCULATION. "In tissue harvested 24 hours after reperfusion, significant changes in gene expression were seen as early as after 1 hour of ischemia: PECAM-1 (3x), MUC1 (6x), and TNF-α (3x)." (PMID 31923917, 2020).
kidney damage (1 paper, 2023). "Variants in NAT8, and CELF2 were associated with microalbuminuria, MUC1, and rs1077216 with UACR and AS3MT with kidney damage (p < 0.001)." (PMID 37446387, 2023).
Lewis lung carcinoma (1 paper, 2025). "The vaccine was tested prophylactically in MUC1 transgenic mice (MUC1.Tg), which exhibit tolerance to engrafted MUC1 transfected Lewis lung carcinoma (LLC) murine cells." (PMID 40284463, 2025).
liver cirrhosis (1 paper, 2019). "The role of mucins in liver cirrhosis is mostly confirmed by clinical works, usually concerning MUC1." (PMID 30875782, 2019).
lobular carcinoma (1 paper, 2023). "In case 5, MUC1 was expressed in the cell lumen, the expression around the cell membrane was strongly positive, and the expression was significantly enhanced compared with the surrounding lobular carcinoma." (PMID 37337182, 2023).
lung adenoma (1 paper, 2013). A benign, well circumscribed epithelial neoplasm that arises from the bronchus or the lung parenchyma. "MUC1.Tg mice treated with urethane alone developed lung adenomas with a tumor incidence rate of 100%, while urethane in combination with DES resulted in tumor incidence rates of 50% and 67% at the 7- and 14-mg/kg DES dose levels, respectively." (PMID 23496860, 2013). "Furthermore, it is evident that urethane alone at a dose of 0.75 mg/g injected weekly for 10 weeks was sufficient to induce lung adenomas in MUC1.Tg C57BL/6 mice." (PMID 23496860, 2013).
lung tumors (1 paper, 2013). "Urethane-induced lung tumors in hMUC1.Tg mice can be used as a model to assess the efficacy of the MUC1 antigen-specific cancer immunotherapeutic agent L-BLP25." (PMID 23496860, 2013).
medullary carcinomas (1 paper, 2023). "Earlier, a study showed that in a BC patient cohort, MUC2 was expressed in all mucinous carcinomas, 11.2% of invasive ductal carcinomas, and none of the invasive lobular and medullary carcinomas, whereas MUC1 was expressed in invasive BC, but not in medullary carcinomas." (PMID 36980526, 2023).
metabolic syndrome (1 paper, 2019). A cluster of metabolic risk factors for CARDIOVASCULAR DISEASES and TYPE 2 DIABETES MELLITUS. "For example, MUC1, SLC2A9, GCKR, and PKD2 may influence other metabolic syndrome–related traits such as blood pressure and FG." (PMID 31408958, 2019).
metastatic colorectal cancer (1 paper, 2025). "NKG2D CAR-NK cells have shown improved cytotoxicity and early signs of safety in metastatic colorectal cancer, while iPSC-derived MUC1-CAR-NK cells selectively eliminate MUC1+ oral tongue carcinoma with minimal toxicity." (PMID 41487532, 2025).
Moyamoya disease (1 paper, 2025). Moyamoya disease (MMD) is a rare intracranial arteriopathy involving progressive stenosis of the cerebral vasculature located at the base of the brain causing transient ischemic attacks or strokes. "RGS1, MUC1, KCNA2, TAC1, and SOST were all found to be up-regulated in moyamoya disease." (PMID 40462179, 2025).
mucinous adenoma (1 paper, 2025). "These cells and their derived tumors show positive expression for the CK7, PAX8, and MUC1 proteins, confirming that they are of epithelial origin, possibly from mucinous adenoma or borderline lesion." (PMID 40427213, 2025).
mucinous ovarian cancer (1 paper, 2023). An invasive malignant neoplasm that arises from the ovary and is characterized by the presence of malignant epithelial cells that contain intracytoplasmic mucin and may resemble the epithelial cells of the endocervix or gastrointestinal tract. "They found that MUC1 can be used as a new biomarker to differentiate between primary and metastatic mucinous ovarian cancer." (PMID 37664708, 2023).
multiple sclerosis (1 paper, 2024). A progressive autoimmune disorder affecting the central nervous system resulting in demyelination. "MUC1 was also found related to central nervous system diseases such as multiple sclerosis." (PMID 38858783, 2024).
myelogenous leukaemia (1 paper, 2018). "• Induction of myeloid-derived suppressor cells (MDSCs) by MUC1 in acute myeloblastic/myelogenous leukaemia (AML) cells has also been reported." (PMID 29784646, 2018).
ocular infection (1 paper, 2019). "MUC1 is thought to prevent damage and infection of the ocular surface epithelium through interactions with galectin-3, however animal models and in vivo work have found inconsistent expression and functions of MUC1 in ocular infection and disease." (PMID 31552195, 2019).
ovarian clear cell adenocarcinoma (1 paper, 2021). A malignant glandular epithelial neoplasm characterized by the presence of clear and hobnail cells. "In our previous study, the most predominant mucin expressed by the ovarian clear cell adenocarcinoma cell lines tested was MUC1." (PMID 34641504, 2021).
Ovarian cyst (1 paper, 2025). The presence of one or more cysts of the ovary. "CA19-9 antigens were immobilized from ascites fluids, ovarian cyst fluids or serum samples using monoclonal antibody C192 followed by probing of carrier proteins using anti-MUC16, anti-MUC1 and, anti STn antibodies and seven lectins, all separately coated on nanoparticles." (PMID 39863644, 2025).
ovarian endometriosis (1 paper, 2021). A non-neoplastic disorder characterized by the growth of endometrial tissue in the ovaries. "We performed RWR algorithm analyses of the ceRNA network using four validated ovarian endometriosis-related genes (ESR1, SNCG, PTCH1, and MUC1) as seed nodes, prioritizing ovarian endometriosis-related lncRNAs, and we also performed permutation tests." (PMID 33584822, 2021).
papillary carcinoma (1 paper, 2014). A malignant epithelial neoplasm characterized by a papillary growth pattern. "In case of papillary carcinoma, we observed moderate to strong staining of MUC1 in the apical layer in majority of the tissue sections." (PMID 24671186, 2014). "Interestingly, some of the epithelial cells showed much higher staining for MUC1 in comparison to cells in the vicinity in some cases of papillary carcinoma." (PMID 24671186, 2014). "Also, the same study demonstrated an increased expression of MUC1 with increasing grade of papillary carcinoma i.e. 37.5% of grade 1 cases, 75% of grade 2 cases and 88.9% of grade 3 cases and this difference in expression was statistically significant (P<0.01)." (PMID 24671186, 2014). "For MUC1, papillary carcinoma cases were restricted to tissue sections alone, as no tissue spot in TMA corresponded to invasive or non-invasive papillary carcinoma." (PMID 24671186, 2014).
parasite infection (1 paper, 2022). "We found TFF1-3, MUC1, MUC6, and MUC20 expression in the bovine abomasal organoids reported here, which is consistent with their feasibility as a relevant in vitro culture model for studying host responses to parasite infection." (PMID 35846775, 2022).
plasmacytoma (1 paper, 2024). Plasmacytoma is a localized mass of neoplastic monoclonal plasma cells that represents approximately 5% of all plasma cell neoplasms. "Plasmacytomas of the clear cell type that express the post-germinal centre and plasma cell markers MUM-1, CD138, CD38, kappa, lambda and MUC-1." (PMID 39465766, 2024). "Immunohistochemistry in this case was negative for CD138, kappa, lambda and MUC-1, although CD38 and MUM-1 were expressed, still ruling out a plasmacytoma." (PMID 39465766, 2024).
polycystic ovarian syndrome (1 paper, 2023). "Intuitively, a higher expression of MUC1 has recently been demonstrated to lead to impaired endometrium receptivity and decidualisation in mice and women with polycystic ovarian syndrome (PCOS)." (PMID 36282011, 2023).
Pseudomonas infection (1 paper, 2022). Infections with bacteria of the genus pseudomonas. "MUC1 has been suggested to play an anti-inflammatory role during Pseudomonas aeruginosa respiratory infection, as Muc1−/− mice are more susceptible to infection in a repetitive Pseudomonas infection model." (PMID 35774401, 2022).
pyometra (1 paper, 2024). "To test whether FOXA2 transcriptional activity was elevated in CLCa KO mice, we analysed the expression of FOXA2 target genes including Ltf and Muc1 in the uterus of WT, CLCa KO, and CLCb KO mice and CLCa KO mice with pyometra." (PMID 37923360, 2024). "However, a layer of MUC1 was observed at the apical surface of endometrial epithelia of the uterine lumen from WT, CLCa KO, and CLCb KO animals, suggesting that a loss of apical MUC1 is not the cause of pyometra in CLCa KO animals." (PMID 37923360, 2024).
renal adenocarcinoma (1 paper, 2017). "To investigate whether tumor irradiation augments the immune response to MUC1 tumor antigen, we have tested the efficacy of tumor irradiation combined with an MVA-MUC1-IL2 cancer vaccine (Transgene TG4010) for murine renal adenocarcinoma (Renca) cells transfected with MUC1." (PMID 28116088, 2017).
renal fibrosis (1 paper, 2026). A final common manifestation of a wide variety of chronic kidney diseases characterized by glomerulosclerosis and tubulointerstitial fibrosis. "In the context of renal fibrosis phenotype ontology (RENAL_FIBROSIS), upregulation was observed in ANTXR1, MUC1, SLC37A4, and NPHP4, while ARL3 and NPHP3 were significantly downregulated." (PMID 41573374, 2026).
renal tumours (1 paper, 2024). "The study highlighted that while MUC1 is expressed in both tumour types, its stronger and more consistent expression in ChRCC makes it a useful marker in the differential diagnosis between these two renal tumours." (PMID 39684226, 2024).
RSV bronchiolitis (1 paper, 2023). "In summary, we found that MUC1 protein levels were significantly increased in the sputum of children with RSV bronchiolitis during the exacerbating phase, indicating that MUC1 may be positively associated with the progression of RSV infection." (PMID 38036963, 2023). "In this study, we first revealed very high MUC1 protein levels in the exacerbation phase in sputum samples from children with RSV bronchiolitis." (PMID 38036963, 2023).
salivary gland carcinoma (1 paper, 2022). A carcinoma that arises from the major or minor salivary glands. "The current study aimed to determine the expression rate of Mucin-1 (MUC1), Mucin-16 (MUC16), and Mucin-5AC (MUC5AC) in salivary gland carcinomas (SGC) using immunohistochemistry." (PMID 35389164, 2022).
serous ovarian tumors (1 paper, 2020). "Tn/STn-MUC16 and MUC1 glycoforms are differently expressed in borderline and malignant serous ovarian tumors from benign lesions, suggesting this glycoform signature as a promising tumor-associated biomarker." (PMID 33019700, 2020).
small intestinal carcinoma (1 paper, 2014). "We also previously examined mucin expression in small intestinal carcinoma, and found positive expression rates of MUC1, 51.7%; MUC2, 26.7%; MUC3, 55.0%; MUC4, 51.7%; MUC5AC, 33.3%; MUC6, 10.0%; and MUC16, 8.3% (MUC17 expression was not examined)." (PMID 25551773, 2014). "Appendiceal carcinoma was MUC1-positive in about half of the cases, similarly to small intestinal carcinoma, but other mucin profiles were different." (PMID 25551773, 2014).
Streptococcus pneumoniae infection (1 paper, 2025). "For instance, Muc1−/− mice exhibit exaggerated pulmonary inflammation and delayed recovery in response to Pseudomonas aeruginosa or Streptococcus pneumoniae infection compared with wild-type controls." (PMID 41181093, 2025).
tubulointerstitial nephritis (1 paper, 2024). "Notably, a similar phenotype is often observed in patients with heterozygous variants of UMOD, MUC1, and REN genes, which cause an autosomal dominant form of tubulointerstitial nephritis." (PMID 38674137, 2024).
type 1 diabetes (1 paper, 2020). "Inevitable treatment with insulinin type 1 diabetes caused overexpression of Muc1; however, ovulationinduction partially moderated such effects and restored Muc1 levels closerto normal values." (PMID 33098389, 2020).
venous thromboembolism (1 paper, 2024). Occlusion of the lumen of a vein by a thrombus that has migrated from a distal site via the blood stream. "The MUC1 levels did not significantly differ between cancer patients with and without venous thromboembolism (VTE)." (PMID 39061213, 2024).
ventilator-associated pneumonia (1 paper, 2021). Serious INFLAMMATION of the LUNG in patients who required the use of PULMONARY VENTILATOR. "Here, we asked whether Pa in the lungs of patients with ventilator-associated pneumonia might also increase MUC1-ED shedding." (PMID 34811449, 2021).
tumor (1,830 papers, 1980 to 2026). "An aberrantly glycosylated and overexpressed form of MUC1 occurs in many human epithelial cancers and was termed tumour-associated MUC1 (TA-MUC1); it is considered as a potential target for cancer therapy." (PMID 41516394, 2026). "In a previous study we identified MUC1-expressing tumors as an immune-silent subgroup of ccRCC, characterized by low immune infiltration, low expression of PD-L1, high M2-like tumor-associated macrophages response, and metabolic reprogramming." (PMID 41533164, 2026). "Tumour-associated MUC1 with aberrant glycosylation is over-expressed in OC and TNBC and acts essentially in tumor metastasis and progression." (PMID 40007813, 2025). "This flavonoid compound also downregulates the gastric epithelium glycoprotein Mucin 1 (MUC1) and other tumor-associated antigens." (PMID 40941879, 2025). "This study revealed that Tn‐MUC1 was expressed in SDC tumor cells, suggesting its potential as a new diagnostic marker for SDC." (PMID 40844495, 2025). "Aberrant glycosylation, particularly of mucins such as MUC1, drives the expression of tumor-associated carbohydrate antigens (e.g., Tn and sialyl-Tn [STn])." (PMID 41228299, 2025). "Our data demonstrated that high Wee1 expression levels sensitized MUC‐1 to AZD1775 anti‐tumour effects, causing a further reduction in cell proliferation and increase in apoptotic cells." (PMID 39528354, 2025). "In MMR-proficient tumours, higher expression of MUC1 was associated with increased densities of macrophages, mature and immature monocytic cells, and granulocytes." (PMID 39966658, 2025). "A DNA vaccine encoding MUC1 and survivin fusion antigens, VR-MS, increased in vitro killing of MUC1+ survivin+ B16 cells and significantly delayed tumor growth using a 100 μg dose." (PMID 41012179, 2025). "The most common method for creating ex vivo DC vaccines for NSCLC is to separate patient autologous monocytes, turn them into DCs, and then load them with tumor-associated antigens (TAAs), like mucin 1 (MUC1), Wilms’ tumor 1 (WT1), or customized neoantigens." (PMID 41002418, 2025). "Several studies have also shown that overexpression of MUC1 is closely associated with tumour malignancy and poor prognosis, especially in carcinomas." (PMID 40144054, 2025). "Nevertheless, some researchers recently engineered CAR-T cells using the variable fragments of a novel monoclonal antibody, TAB004, which specifically binds the tumor-associated-MUC1 (tMUC1) to PDA cells, showing promising cytotoxic activity." (PMID 40001578, 2025). "While MAGEA3 and MUC1 have been established as immunogenic tumor antigens capable of generating anti-tumor T cell responses, it is possible that encoding only one tumor antigen in a lung cancer vaccine formulation is not sufficient to broadly prolong survival." (PMID 41542091, 2025). "It depicts the mechanism by which CAR-T cells recognize and bind to specific tumor-associated antigens, including folate receptor alpha (FRα), mucin-1 (MUC1), and epithelial cell adhesion molecule (EpCAM)." (PMID 40281554, 2025). "Percentages are calculated from the total number of tumor-associated MUC1 (TA-MUC1)–positive cases (n = 73)." (PMID 41322748, 2025). "Bispecific CAR T-cells targeting HER2 alongside other tumor-associated antigens (e.g., gp100 or MUC1) have shown enhanced cytotoxicity against breast tumors in preclinical models." (PMID 40940995, 2025). "Tumor-associated MUC1 on the surface of the epithelial cell has a reduced density and length of the N-glycosylated terminal domain." (PMID 40699615, 2025). "Like other CAR-T therapies, MUC1-targeted treatments can cause on-target, off-tumor toxicities because of the low-level expression of MUC1 on normal tissues." (PMID 40312353, 2025). "TA-MUC1-directed antibodies and ADCs such as gatipotuzumab (PankoMab-GEX) - a humanized IgG1 antibody recognizing the tumor-associated MUC1 epitope (TA-MUC1)." (PMID 41322748, 2025).